PDE7B (phosphodiesterase 7B)
Diseases named in the same sentence as PDE7B in open-access papers (continued):
Sharing a sentence is not in itself a finding about the gene and the disease.
tumor (continued). "The increase in blood vessel density in wild type tumors also suggests that tumor cell PDE7B might function as part of a positive feedback loop for promoting angiogenesis." (PMID 25203500, 2014). "Furthermore, PDE7B overexpression inhibits tumor proliferation and metastasis in vitro." (PMID 38778317, 2024). "Furthermore, PDE7B might be a tumor suppressor in ccRCCs, and our study suggests that PDE7B could have a similar role in HCC." (PMID 38778317, 2024). "However, sorafenib’s antitumor effect may be enhanced, potentially compensating for the tumor-promoting advantage brought about by low PDE7B expression." (PMID 39640266, 2024). "Therefore the induction of PDE7B expression in tumor cells localized to the perivascular space may function to promote CSC function." (PMID 25203500, 2014). "Elevated PDE7B expression has been reported in GBM cases, negatively impacts patient survival, and promotes the expansion of stem-like cancer cells and increased tumor aggressiveness in vitro and in vivo." (PMID 41179677, 2025). "Therefore, the function of PDE7B may differ among tumor tissues and cells." (PMID 38778317, 2024). "Therefore, we speculate that PDE7B may affect tumor progression by regulating cAMP levels." (PMID 39640266, 2024). "Increased PDE7B expression leads to the inhibition of PDCD1 expression, triggering immune suppression and restraining the invasion and migration abilities of tumor cells." (PMID 39640266, 2024). "In the previous study, miR-200c regulated the overexpression of PDE7B in TNBC cells and were critical for TNBC cell proliferation and tumor development by modulating cellular cAMP concentration." (PMID 32922506, 2020). "Our previous study showed that miR-200c-led inhibition of PDE7B diminished AKT activity to regulate TNBC cell proliferation and tumor growth." (PMID 32922506, 2020). "Together with data regarding PDE7B functions in GBM, these findings indicate that the cAMP pathway is essential for tumor initiating cell function." (PMID 26283963, 2015). "In our study, knocking out PDE7B reduced the hydrolysis of cAMP and activated PKA, which phosphorylated downstream PKA substrates such as CREB, leading to the invasion and migration of tumor cells." (PMID 39640266, 2024). "Though miR-421 has been identified to target multiple mRNAs to alter tumor progression, such as FOXO4, MEF2D, and MTA1, whether miR-421 can target PDE7B remains to be uncovered." (PMID 33817314, 2021).
cancer (6 papers, 2014 to 2024). A tumor composed of atypical neoplastic, often pleomorphic cells that invade other tissues. "Our results demonstrated that overexpression of PDE7B leads to a significant increase in mitochondrial ROS, resulting in elevated cell apoptosis and suppressed proliferation of cancer cells." (PMID 39640266, 2024). "Several investigations have illustrated that the expression of PDE7B is dysregulated in pan-cancer." (PMID 38778317, 2024). "However, few researches have reported the connection between PDE7B and cancer migration, invasion, and proliferation." (PMID 39640266, 2024). "While the role of PDEs in cancer has been widely studied, the specific function of PDE7B in HCC has not been thoroughly explored." (PMID 39640266, 2024). "While there have not been any studies of specific PDE7B inhibitors in the context of cancer treatment, there has been work done evaluating PDE7B inhibition for the treatment of autoimmune disorders." (PMID 25203500, 2014).
central nervous system diseases (1 paper, 2019). "A number of studies have shown that PDE7B may play a role in a variety of central nervous system diseases by affecting cAMP levels, and found that PDE7B may be involved in dopaminergic signaling in striatal neurons and play a key role in memory function." (PMID 31740742, 2019).
inflammation (1 paper, 2019). Aberrant reaction of the microcirculation characterized by movement of fluid and leukocytes from the blood into extravascular tissues. "However, a study showed no involvement of PDE7A and PDE7B in the asthmatic mice model of ovalbumin-induced airway inflammation and hyper-reactivity." (PMID 30696075, 2019).
PDE7B also shares sentences with these, for which no sentence is quoted: asthma (3 papers); osteosarcoma (3); type 2 diabetes (2); acute myeloid leukemia (1); Alzheimer disease (1); diabetes (1); Insulin resistance (1); Intellectual disability (1); internal carotid artery stenosis (1); mantle cell lymphoma (1); renal clear cell carcinoma (1); Stroke (1); triple-negative breast carcinoma (1).